FAP (fibroblast activation protein alpha)
Diseases named in the same sentence as FAP in open-access papers (continued):
Sharing a sentence is not in itself a finding about the gene and the disease.
tumor (continued). "The role of FAPα is controversial as it remains associated with tumor promotion and inhibition; therefore, the clinical significance of FAPα expression requires further study." (PMID 25593080, 2015). "Increasing evidence has suggested that the expression of the membrane-bound FAP in various solid tumors is associated with tumor growth and invasion and poor prognosis." (PMID 24520291, 2014). "FAP is the type II membrane dipeptidylpeptidase, and its expression has been reported to associate with fibroblasts in the tumor stroma." (PMID 24605102, 2014). "The in vitro tumor growth assay was used for the detection of change in growth caused by FAP knockdown in HOS and MG-63 cells." (PMID 24520291, 2014). "To ensure our tumor epithelial cell isolates were free of fibroblasts, we tested our cells for the presence of a-smooth muscle actin and fibroblast activated protein (FAP), markers for tumor-associated fibroblasts." (PMID 26273699, 2014). "Fibroblast activation protein (FAP) is predominantly expressed on the surface of reactive tumor-associated fibroblasts as well as on particular cancer types." (PMID 23937772, 2013). "Because of its specific induction in tumor-associated fibroblasts in over 90% of epithelial tumors, including pancreas and breast among others, FAP was used as a platform for studying stromal specific effects on tumor behaviors." (PMID 21668992, 2011). "In this study, Fibroblast activation protein (FAP), a serine protease selectively produced by tumor-associated fibroblasts in over 90% of epithelial tumors, was used as a platform for studying tumor-stromal interactions." (PMID 21668992, 2011). "FAP is expressed in wounds and fibrotic tissues as well as carcinoma-associated fibroblasts in multiple cancer types and is thought to degrade tumor matrix and facilitate carcinoma invasion." (PMID 20646316, 2010). "Kaplan–Meier survival analysis in MRI‐visible tumours showed that high stromal and epithelial FAP were associated with shorter BCR‐free survival (log‐rank test, p = 0.02 and p = 0.01, respectively), whereas high stromal αSMA was associated with longer BCR‐free survival (p = 0.02)." (PMID 41410015, 2026). "Compared with [18F]fluoro-2-deoxy-D-glucose ([18F]FDG), which reflects glucose uptake in metabolically active regions, FAPIs mainly bind to the fibroblast activation protein (FAP), which is highly expressed in tumor-associated fibroblasts, forming a pronounced signal." (PMID 41750670, 2026). "In contrast, the high-risk group was enriched for CD66b+/MMP9+ (pro-tumor neutrophils), FAP+/collagen IV+ (extracellular-matrix-remodeling fibroblasts) and CD163+/MMP9+ (M2-like tumor-associated macrophages), reflecting distinct tumor microenvironments between the two groups." (PMID 41491099, 2026). "Hence, FAP regulates signaling pathways that promote tumor growth and angiogenesis and was reported to be associated with antitumor immune responses." (PMID 40694103, 2026). "Additionally, targeting fibroblast activation protein (FAP)-expressing cancer-associated fibroblasts (CAFs) has been shown to remodel the tumor stroma and promote T cell infiltration in tumor models." (PMID 41596556, 2026). "FAP is a cell surface serine protease highly expressed on cancer-associated fibroblasts that promotes tumor progression by remodeling the extracellular matrix and suppressing anti-tumor immune responses." (PMID 41590379, 2026). "Given that FAP is a glycoprotein transmembrane receptor found on cancer-associated fibroblasts (CAFs), differentiating between tumor and non-tumor lesions may be more effective using this method." (PMID 39744055, 2025). "Moreover, we identified 4 distinct CAF subtypes expressing FAP, that were specifically enriched in regions of tumor-stroma interface and associated with tumor cells and CD44+ macrophages." (PMID 40292277, 2025).
tumor (continued). "Our flow cytometry analysis demonstrated that the conditional medium from Antrocin-treated cells was significantly less capable of generating cancer-associated fibroblasts (CAFs) and M2 tumor-associated macrophages (TAMs), as evidenced by decreased FAP and CD206 expression, respectively." (PMID 41009348, 2025). "This heterogeneity in expression levels was especially evident in the DLBCL cases, which may indicate underlying biological differences in FAP regulation or tumor heterogeneity." (PMID 41373408, 2025). "Similarly, 68Ga-FAPI, which targets fibroblast activation protein (FAP), helps visualize tumor-associated stroma and its role in cancer progression, including hypoxia-induced changes in the tumor microenvironment." (PMID 41333220, 2025). "Alterations in circulating FAP concentrations may result from tumor-associated changes in fibroblast activity or systemic protease activity, which could modulate FAP production or clearance." (PMID 40690098, 2025). "In cancer, FAP has been implicated in a variety of tumor-promoting processes." (PMID 41373408, 2025). "In fact, we recently demonstrated, using multiplex immunofluorescence, that the co-localization of FAP + CAFs with these immune cells within the tumor microenvironment was independently associated with reduced survival, reinforcing the pathogenic synergy among these components." (PMID 41303595, 2025). "To resolve this problem, we adopted a simplified approach involving a single-stain IHC evaluation of FAP+ CAFs, which are widely recognized as a tumor-promoting and immunosuppressive subtype of CAFs closely associated with tumor progression and poor clinical outcomes." (PMID 41154405, 2025). "Its combination with FAP, expressed by both EC cells and cancer-associated fibroblasts, as part of the tumor microenvironment, may facilitate immune evasion and promote tumor infiltration." (PMID 41345672, 2025). "FAP is selectively overexpressed on cancer-associated fibroblasts (CAFs) in 80–95% of epithelial tumours and certain mesenchymal malignancies, where it plays a multifaceted role in tumour progression." (PMID 40725089, 2025). "Taken together, these findings support the role of FAP as a marker of tumor aggressiveness, risk stratification and therapeutic response, and warrant further investigation into its integration into routine pathological assessment and clinical decision-making in ccRCC." (PMID 41303595, 2025). "Additionally, the co-occurrence of elevated FAP + CAFs, T-cyt, T-reg, and macrophages at the tumor center was independently linked to worse CSS." (PMID 39751643, 2025). "This approach is crucial as certain subgroups of leukocytes are known to be partially FAPα+ and may represent tumor-associated macrophages." (PMID 39815324, 2025). "FAP is a serine protease that is expressed in fibroblasts and is associated with pathophysiologic tissue remodeling, including in inflammatory and fibrotic diseases and tumor stroma." (PMID 40232854, 2025). "Fibroblast Activation Protein (FAP), a pivotal marker and mediator expressed by CAFs, has emerged as a significant diagnostic, therapeutic, and prognostic target due to its multifaceted roles in the tumour microenvironment." (PMID 40741380, 2025). "In addition, previous studies have demonstrated that high expression of FAP is associated with a worse prognosis in various tumours, including PC and BTC." (PMID 40076605, 2025). "Because FAP is overexpressed in tumors and tissue remodeling sites and its expression is difficult to detect in non-diseased adult organs, it has recently been reported as a tumor-specific therapeutic and diagnostic target." (PMID 40126602, 2025). "By analyzing a well-characterized cohort of synchronous and metachronous metastatic cases treated with TKIs, we confirmed that stromal FAP expression is significantly associated with pathological features of aggressive disease, such as higher tumor stage and histological grade." (PMID 41303595, 2025).
tumor (continued). "However, the development of radionuclide therapy targeting CAF-specific markers, such as FAP, for diagnostic and therapeutic purposes offers new hope for overcoming tumor immunosuppression and improving the efficacy of radiotherapy." (PMID 40244052, 2025). "Fibroblast activation protein (FAP) is a transmembrane serine protease with high expression on cancer-associated fibroblasts (CAFs) in more than 90% of epithelial carcinomas and on some tumor cells of mesenchymal origin." (PMID 41460404, 2025). "Taken together, last decades' radiopharmaceuticals have been primarily targeting tumor cell membrane proteins (B7-H3, CXCR4, FRα, HER2, integrin αVβ3, L1CAM, mesothelin, MISRII and NaPi2b) besides the (intra-)nuclear target PARP-1 and the FAP-associated tumor microenvironment." (PMID 39431018, 2024). "Pan-cancer analysis of TCGA database has provided evidence that individuals with high POSTN or FAP expression are associated with a high Tumor Immune Dysfunction and Exclusion (TIDE) score, indicating greater potential for immune evasion and unfavorable prognosis from immunotherapy." (PMID 39107856, 2024). "Cancer-associated fibroblasts have FAP as a target, which is highly specific to tumor expression." (PMID 39272726, 2024). "Fibroblast Activating Protein (FAP), a type‐II transmembrane serine protease, is notably expressed in cancer‐associated fibroblasts (CAFs) within the stroma of epithelial carcinomas and tumor stroma." (PMID 40337455, 2024). "Peptides, owing to their potential for heightened receptor selectivity, binding affinity, and tumor retention, may outstrip other FAP inhibitors in the realms of diagnostic and therapeutic efficacy." (PMID 38543239, 2024). "Osteosarcoma shows heightened FAP linked to tumor size and stage." (PMID 38558814, 2024). "Interestingly, increased FAP expression in pancreatic cancer has been associated with lymph node metastasis and tumor recurrence." (PMID 39579201, 2024). "Moreover, immunofluorescence with α-SMA and FAP markers confirmed the presence of tumor-associated MSCs in the heterotypic spheroids." (PMID 38532439, 2024). "When comparing tracer uptake in pulmonary lesions among the three groups, G1 showed higher imaging agent activity, likely due to the dense presence of tumor-associated fibroblasts and high FAP expression in the Tumor Microenvironment (TME) of primary lung tumors." (PMID 38779097, 2024). "Similarly, fibroblast activation protein (FAP)-targeted radiopharmaceuticals that bind to tumour-associated fibroblasts, which are increased in dedifferentiated and more aggressive DTCs, have also been investigated." (PMID 39336848, 2024). "Addressing FAPα offers a novel approach for tumor imaging by focusing on tumor-associated cells." (PMID 39410013, 2024). "In recent years, fibroblast activation protein (FAP), a cell membrane bound type II serine protease, has emerged as a marker for identifying several tumor types due to its presence in the tumor stroma and has been shown to be associated with worse outcomes in many tumors." (PMID 39664608, 2024). "In pancreatic ductal adenocarcinoma (PDAC), FAP overexpression is found not only in tumor stroma but also in the PDAC cells and may be associated with metastatic spread and worse clinical outcome." (PMID 40604259, 2024). "However, BC and RCC did not exhibit an upregulated angiogenesis gene signature associated with FAP expression, potentially suggesting diverse mechanisms of tumor vascularization or alternative nutrient supply routes in these cancer types." (PMID 39035007, 2024). "The transmembrane glycoprotein fibroblast activation protein (FAP) is highly expressed in the tumor microenvironment/stroma, cancer-associated fibroblasts (CAFs), and pericytes, accounting for the predominant portion of the tumor mass." (PMID 37584717, 2024).
tumor (continued). "Given the prevailing literature that supports a generally more benign phenotype for HPV-positive HNSCC, these results fortify the hypothesis that FAP expression is intricately associated with the tumor's malignancy grade." (PMID 38826849, 2024). "Thus, FAP overexpression is associated with tumor immunomodulation leading to increased local tumor invasion, metastasis, and overall poor prognosis." (PMID 35997853, 2023). "Another approach could be to counter the inhibitory effect of the tumour microenvironment, for example, by attacking tumour-associated myofibroblasts through their expression of FAP (Fibroblast Activating Protein)." (PMID 37190286, 2023). "We here describe a potency-matched dual-cytokine antibody fusion protein containing a tumor-targeting antibody fragment specific to human fibroblast activation protein (FAP), simultaneously linked to both interleukin-2 (IL2) and a tumor necrosis factor (TNF) mutant." (PMID 37092450, 2023). "Moreover, FAP is associated with tumour progression by supporting angiogenesis, immunosuppression, and drug resistance." (PMID 37631053, 2023). "FAP is overexpressed in cancer-associated fibroblasts (CAFs) located in tumor stroma, and is known to be involved in a variety of tumor-promoting activities such as angiogenesis, proliferation, resistance to chemotherapy, extracellular matrix remodeling and immunosuppression." (PMID 39355017, 2023). "FAP is strongly and broadly expressed in tumor stroma, associated with tissue remodeling, and it potentially may correlate to tumor progression." (PMID 38004406, 2023). "Fibroblast activation protein (FAP) is commonly overexpressed in cancer-associated fibroblasts, which are known to be the primary components of stromal cells that contribute up to 90% of the tumor mass." (PMID 36522509, 2023). "Moreover, lower expression level of MYB was detected in FAP (+) tumor-associated fibroblasts, suggesting a potential relationship between tumor microenvironment and MYB." (PMID 36994664, 2023). "FAP is overexpressed by cancer-associated fibroblasts of several tumor types." (PMID 36813980, 2023). "FAP expression was proven to be associated with a poor prognosis in a kind of malignant tumor, and its overexpression in cancer-associated fibroblasts made it an ideal target for tumor imaging and therapy." (PMID 37057133, 2023). "FAP is considered a protein specifically expressed by CAFs, and by using FAP as a target for CAFs, the development of FAP monoclonal antibodies and small molecule inhibitors of FAP enzyme activity has been used in tumor therapy as well as diagnostic imaging." (PMID 36838669, 2023). "Several studies have shown that a depletion in FAP-positive CAFs restricted tumor growth by enhancing antitumor immunity, which occurs through multiple mechanisms, including loss of immunosuppressive effects of stromal cells or enhancement of tumor survival." (PMID 38136299, 2023). "In addition, FAP has notably been linked with a poor prognosis by enhancing tumor growth, matrix remodeling and angiogenesis." (PMID 37376181, 2023). "Notably, mCAFs highly expressed tumor invasion-associated genes (FAP, MMP1, MMP14, and POSTN), commonly associated with ECM remodeling and cell migration during tumor metastasis, thus reflecting the importance of mCAFs in the metastatic TME." (PMID 37853464, 2023). "Finally, there is a general agreement on the negative prognostic role of CAFs in various solid tumors (including BC), with high FAP expression associated with a more aggressive tumor behavior, disease progression and treatment resistance." (PMID 36765866, 2023). "Additionally, microarray analysis detected high EIF4A3 expression in FAP (+) tumor-associated fibroblasts." (PMID 37777564, 2023). "Studies have shown that FAP is highly expressed in 90% of epithelial tumors, including prostate, pancreatic, colon, and breast cancers, and is expressed by the cancer-associated fibroblasts (CAFs) in the tumor microenvironment (TME)." (PMID 36986548, 2023).
tumor (continued). "While under pathological circumstance, due to excessively remodeling extracellular matrix and abnormally altering intracellular signaling pathways, FAP is linked to multiple pathologies including liver cirrhosis, pulmonary fibrosis, Crohn’s disease, arthritis, atherosclerosis, and even tumor." (PMID 37166418, 2023). "Radiolabeled fibroblast activation protein (FAP) inhibitors (FAPIs) have shown promise as cancer diagnostic agents; however, the relatively short tumor retention of FAPIs may limit their application in radioligand therapy." (PMID 37321827, 2023). "We demonstrate that FAP is upregulated in various cancer types, and increased FAP expression is associated with advanced pathological stages, poor prognosis and immunosuppressive tumor microenvironment." (PMID 37166418, 2023). "Indeed, FAP inhibition to eradicate CAFs has been associated with decreased collagen content and tumor burden, and improved immunotherapy effectiveness." (PMID 36358839, 2022). "Furthermore, high expression levels of FAP is associated with increased local tumor invasion, lymph node metastasis, and decreased overall survival rates in many malignancies, whereas FAP inhibition can attenuate tumor growth." (PMID 35962347, 2022). "Fibroblast activation protein (FAP) is overexpressed in cancer-associated fibroblasts, which are one of the main tumor stroma components and constitute a major proportion of cells within the tumor." (PMID 34593598, 2022). "Furthermore, studies which target FAP expressed on cancer-associated fibroblasts or VEGFR-2 expressed on tumor vasculature endothelial cells have shown that tumor stroma is genetically more stable." (PMID 36153626, 2022). "Tumours high in FAP+CAFs are positively associated with an increase in FoxP3+ Treg infiltration." (PMID 35479076, 2022). "Overall, FAP expression in tumor cells and the combination FAP expression in tumor cells and CAFs were strongly associated with patient survival and may be useful predictive biomarkers for patient outcomes in NSCLC." (PMID 35818720, 2022). "A high expression of FAP in tumor tissue is associated with poor patient prognosis." (PMID 35186170, 2022). "The elevated level of FAP expression was linked to a more advanced tumor stage in STAD." (PMID 35359436, 2022). "Antigen FAP was mentioned for cancer-associated fibroblasts in the tumor stroma." (PMID 36051919, 2022). "Conversely, FAP-positive tumour cells expressed significantly lower levels of genes encoding epithelial junction proteins (including CDH1, JUP, CTNN1A) epithelial differentiation markers, including several keratins (6B, 7, 17, 19, 23) and mucins (1, 3A, 4, 12), and chemokines (CXCL1-3, 5, 6)." (PMID 35296803, 2022). "Our data demonstrated that GPX8 was correlated with mRNA expression of immune markers of CD8+ T cells (CD8B), CD4+ T cells (CD4), T cells (CD3D), macrophages (CD68 and ARG1), neutrophils (ITGAM and CCR7), dendritic cells (NRP1), NK cells (B3GAT1), and tumor-associated fibroblasts (FAP)." (PMID 36061208, 2022). "Although the immunomodulatory effects of CAFs are predominantly immunosuppressive and tumour-promoting, in melanoma a podoplanin (PDPN)+, FAP- CAF subtype has been shown to act in an immunostimulatory manner via development of tumour-associated tertiary lymphoid structures (TA-TLS)." (PMID 36313650, 2022). "However, limitations remain due to the suboptimal specificity of those FAPI molecules to cancer-associated FAP substrate, rapid clearance from the systemic circulation, and short retention time in the tumor." (PMID 34681246, 2021). "In cancer, FAP plays a role in extracellular matrix digestion and cancer invasion through its gelatinase activity; it is associated to a proangiogenic environment, and its expression has been correlated with tumor immunosuppression." (PMID 33562504, 2021).